S100P (S100 calcium binding protein P)
Diseases named in the same sentence as S100P in open-access papers (continued):
Sharing a sentence is not in itself a finding about the gene and the disease.
cholangiocarcinoma (13 papers, 2014 to 2024). A carcinoma that arises from the intrahepatic biliary tree (intrahepatic cholangiocarcinoma) or from the junction, or adjacent to the junction, of the right and left hepatic ducts (hilar cholangiocarcinoma). "Immunohistochemistry showed positivity for S100P, a marker of malignant transformation, leading to the diagnosis of well-differentiated intrahepatic cholangiocarcinoma of large duct type." (PMID 38514507, 2024). "S100P has been reported as a prognostic signature in cholangiocarcinoma and hepatocellular carcinomas." (PMID 36556252, 2022). "Previous studies have shown that S100P is expressed in cholangiocarcinoma and BilIN lesions in patients with hepatolithiasis." (PMID 33369464, 2020). "However, there was a report that higher expression levels of S100P were detected in cholangiocarcinoma compared with the benign biliary strictures." (PMID 33962620, 2021). "Furthermore, γ-H2AX and S100P expressions were detected in all BilIN lesions in patients with subsequent cholangiocarcinoma." (PMID 33369464, 2020). "We further evaluated the effect of S100P and SPP1 in distinguishing iCCAphl and iCCApps in two RNA-seq databases of cholangiocarcinoma." (PMID 35347134, 2022). "CREB3L1, which is upregulated in S100P + SPP1− intrahepatic cholangiocarcinoma tumor cells, can facilitate the invasion of S100P + SPP1− perihilar large duct type tumor cells by directly targeting S100P." (PMID 36171879, 2022). "All five patients who developed subsequent cholangiocarcinoma had BilIN or IPNB lesions, and the positive expressions of γ-H2AX and S100P were detected in the BilIN lesions of four patients." (PMID 33369464, 2020).
lung adenocarcinoma (10 papers, 2014 to 2025). A carcinoma that arises from the lung and is characterized by the presence of malignant glandular epithelial cells. "In lung adenocarcinoma, upregulation of S100P is closely associated with cytoskeletal reorganization, tumor metastasis, and immune evasion." (PMID 39992528, 2025). "S100P is highly expressed in multiple tumor types, particularly in pancreatic, breast, colorectal, and lung adenocarcinomas, where its expression correlates with cancer invasiveness and metastasis." (PMID 39992528, 2025). "Another interesting case is S100P, which has been reported as a key gene in tumor progression in both initial stage and advanced stage in lung adenocarcinoma." (PMID 27610367, 2016). "Another study shows that targeting three genes, HGF, PTX3, and S100P, or their associated pathways, could be a promising strategy for inhibiting EMT and combating lung adenocarcinoma (LUAD)." (PMID 39201656, 2024). "There are nearly no changes existent in gene expression between normal and T-NDM, while in T-DM, upregulation is observed, which implies that the upregulation of S100P may be an important step in the early stage of lung adenocarcinomas." (PMID 27610367, 2016). "Survival analysis demonstrated that S100P expression significantly influenced patient survival in liver hepatocellular carcinoma (LIHC) and lung adenocarcinoma (LUAD)." (PMID 40224483, 2025). "MRNA expression levels of TIMP1, S100P, HMMR, F2RL1, KRT6A, and SLC2A1 were significantly increased in lung adenocarcinoma cell lines compared to16HBE, which were consistent with our bioinformatics analysis results." (PMID 35830566, 2022).
hepatocellular carcinoma (9 papers, 2013 to 2025). A malignant tumor that arises from hepatocytes. "For example, S100P was found to be significantly associated with early recurrence and poorer clinical outcomes in patients with hepatocellular carcinomas." (PMID 36177001, 2022). "Interestingly, S100p gene, which is associated with Cell Cycle, Cell Growth and Invasion and reported to be a novel independent predictor for poor prognosis in colorectal and hepatocellular carcinoma, was also found upregulated only in vulvar cancer samples in our study." (PMID 26559525, 2015). "Using differential display, we found S100P is overexpressed in human hepatocellular carcinoma (HCC)." (PMID 23785431, 2013). "Univariate analysis of S100P protein expression with various clinicopathological features and aberrant gene expression in 305 patients with surgically removed unifocal primary hepatocellular carcinoma." (PMID 23785431, 2013). "Univariate analysis of clinicopathological variables and S100P protein expression with early tumor recurrence (ETR) in patients with surgical removed unifocal primary hepatocellular carcinoma." (PMID 23785431, 2013). "Additionally, recent research highlights S100P as a ferroptosis inhibitor, promoting hepatocellular carcinoma by reprograming lipid metabolism." (PMID 40224483, 2025). "In hepatocellular carcinoma (HCC), aberrant S100P expression suppresses cell growth and apoptosis by downregulating cyclin D1 and CDK expression at the protein level." (PMID 36187124, 2022).
melanoma (8 papers, 2019 to 2025). A malignant, usually aggressive tumor composed of atypical, neoplastic melanocytes. "S100P and S10012 have a diagnostic and prognostic value in many human cancers, while the contribution of S100A8 and S100A9 to melanoma biology is not fully understood." (PMID 40075679, 2025). "S-100P is produced by certain cells in the immune system and has been found to be elevated in some cases of melanoma and other types of cancer." (PMID 37504268, 2023). "In melanoma patients, vitamin D status was associated with TL (measured/estimated as LDH and S100P s.c.)before and along with treatment with BRAF/MEK and/or ICIs." (PMID 35669434, 2022). "Higher levels of S100P were reported in primary melanoma than in nevi and in metastatic melanoma than in primary tumors." (PMID 33256110, 2020). "Accumulating evidences suggest that the binding of S100P to ezrin could initiate cell migration in malignant melanoma." (PMID 33256110, 2020). "S100 subtypes: S100B, S100P, S100A4, S100A6, and S100A13 are often found in melanoma, with S100P being positive in all melanoma subtypes." (PMID 37504268, 2023). "S100-P, HMB45, and Melan-A negativity in tumor cells ruled out a melanoma." (PMID 37218666, 2024).
ovarian carcinoma (8 papers, 2008 to 2022). A malignant neoplasm originating from the surface ovarian epithelium. "Significant correlation was found between high expression and S100P and shorter overall survival (OS) and increased drug resistance in gastric and ovarian cancer." (PMID 29868478, 2018). "In ovarian cancer, S100P was shown to be positively correlated with CA125 and poor prognosis." (PMID 33815482, 2021). "In ovarian cancer, many S100 family members have been reported, such as S100A1, S100A4, S100A6, S100B and S100P." (PMID 30558666, 2018).
gastric cancer (7 papers, 2011 to 2025). A primary or metastatic malignant neoplasm involving the stomach. "In contrast, S100P is likely to be a pro-survival factor in gastric cancer cells with loss of functional E-cadherin, contributing to an oncogenic molecular program." (PMID 31767037, 2019). "We propose that S100P has a dual role in gastric cancer, acting as an oncogenic factor in the context of E-cadherin loss and as a tumour suppressor in a functional E-cadherin setting." (PMID 31767037, 2019). "The role of S100P was evaluated through in vitro functional assays and its expression was studied in a gastric cancer tissue microarray (TMA)." (PMID 31767037, 2019). "In gastric cancer cells, both b-catenin and DAPK1 expression was regulated by S100P, which is an oncogenic factor in gastric cancer." (PMID 28740751, 2017). "Additionally, S100P promotes endometrial cancer cell proliferation by increasing nuclear translocation of β-catenin, and its downregulation results in gastric cancer cell apoptosis and inhibited cell colony formation by decreasing β-catenin expression." (PMID 33264103, 2020). "The discovery of antagonist effects of S100P in different E-cadherin contexts will aid in the stratification of gastric cancer patients who may benefit from S100P-targeted therapies." (PMID 31767037, 2019). "Moreover, expression analysis in a gastric cancer TMA revealed that S100P expression impacts negatively among patients bearing Ecad− tumours, despite not being significantly associated with overall survival on its own." (PMID 31767037, 2019). "Consistent with its tumor suppressor potential, ectopic expression of latexin induced differential expression of several tumor related genes, including Maspin, WFDC1, SLPI, S100P, and PDGFRB, in gastric cancer cells." (PMID 21466706, 2011). "Similarly, knockdown of S100p in MGC-803 and SGC-7901, 2 gastric cancer cell lines, abrogated the ability of these cells to form colonies through promotion of apoptosis corresponding potentially to a positive association with progression risk in our model." (PMID 41134301, 2025). "We performed Quantitative Real-time PCR (qPCR) on 6 up-regulated genes (COL1A, BGN, SPP1, MELK, IGFBP4, SPARC) and 4 down-regulated genes (PGC, SST, MT1X, S100P) to verify our data in gastric cancer tissues (Tumor) and noncancerous tissues (Normal)." (PMID 25928635, 2015).
pancreatic adenocarcinoma (7 papers, 2012 to 2023). "S100P in pancreatic adenocarcinoma showed a similar trend, with 24.02 and 20.3-fold changes in Iacobuzio-Donahue’s and Logsdon’s datasets, respectively." (PMID 34804125, 2021). "The hypermethylation of S100P was predominantly detected in the normal pancreas, whereas the 3 pancreatic adenocarcinomas showed variable methylation levels, similar to previous observations." (PMID 25585623, 2015). "Several studies examined the usefulness of S100P in the diagnosis of pancreatic adenocarcinoma using EUS-FNA." (PMID 23197977, 2012). "miR-495 by targeting S100P could perform suppressive roles in pancreatic adenocarcinoma." (PMID 35317077, 2022). "Finally, to establish the potential clinical relevance of S100P and S100PBP, we studied TCGA PanCancer Atlas dataset on 176 pancreatic adenocarcinoma patients and generated Kaplan–Meier survival plots." (PMID 37794133, 2023).
COVID-19 (6 papers, 2021 to 2025). A disease caused by infection with severe acute respiratory syndrome coronavirus 2. "Elevated mRNA expression of S100A6, S100A8, S100A9, and S100P, have been identified in the nasal swabs of COVID-19 patients." (PMID 41164170, 2025). "Finally, correlation between S100A6, S100B, S100A8, S100A9, S100A12, and S100P and COVID-19 pathogenesis is discussed." (PMID 35892571, 2022). "Transcriptomic analyses have shown overexpression of S100A8, S100A9, S100P and S100A12 in lung tissue from fatal COVID-19 patients." (PMID 41164170, 2025). "Six human PGs were identified as differentially expressed across the three subsets based on COVID-19 severity: Cytokeratin-4, ADP-ribosylation factor 4, Ig lambda chain V-I region HA, Protein S100-P, Sodium/glucose cotransporter 1, and Ig mu chain C region." (PMID 38188629, 2023).
endometrial cancer (6 papers, 2016 to 2025). Primary or metastatic malignant neoplasm involving the endometrium (mucous membrane that lines the endometrial cavity). "S100P promotes the proliferation, invasion, and migration of endometrial cells and trophoblast cells, and is known to promote the progression of endometrial cancer and facilitate embryo implantation." (PMID 34215278, 2021). "In summary, S100P is expressed highly in endometrial cancer cells, and increases gradually from normal endometrium and SH to CH, to AH and then to EC." (PMID 32883230, 2020). "S100P influences cell invasion by interacting with Ezrin and reconstructing F-actin, which implies its involvement in the occurrence and development of endometrial cancer." (PMID 32883230, 2020). "S100P was mainly distributed in the cytoplasm and co-localized with Ezrin in endometrial cancer cells." (PMID 32883230, 2020). "The expression of S100P in endometrial cancer and its precancerous lesions was observed using immunohistochemistry." (PMID 32883230, 2020). "The results of immunofluorescence showed that the S100P protein had a similar expression trend to the mRNA in endometrial cancer cells." (PMID 32883230, 2020). "Immunohistochemical staining was performed to detect the expression and distribution of S100P in the tissue samples of endometrial cancer and its precursor lesions." (PMID 32883230, 2020). "The present study aimed to investigate the expression of S100P in endometrial cancer and its precursor lesions, and to explore the possible mechanisms." (PMID 32883230, 2020). "S100P: Increased expression of S100P promoted cellular proliferation by increasing the nuclear translocation of β-catenin in endometrial cancer." (PMID 27534621, 2016). "S100P also seems to regulate the activity of β-catenin in endometrial cancer." (PMID 40420099, 2025). "A recent article reported that the expression of S100P progressively increased from grade 1 to grade 3 endometrial cancers, which supported our hypothesis." (PMID 32883230, 2020). "Another study reported that the expression of S100P was elevated in endometrial cancer." (PMID 32883230, 2020). "The significantly higher expression of S100P in endometrial cancer cells suggested that it might play important roles in endometrial cancer, as it does in other cancers." (PMID 32883230, 2020). "Thus, S100P is likely to promote the invasion and progression of endometrial cancer." (PMID 32883230, 2020). "Therefore, the much higher expression of S100P in RL95–2 cells than in Ishikawa cells indicated that the expression of S100P might be related to the degree of malignancy of endometrial cancer." (PMID 32883230, 2020). "Since several other proteins, including S100P, are regulatory components of a novel ubiquitinylation complex involved in β-catenin degradation, further studies are in need with specific regard to trigger for β-catenin nuclear localization in endometrial cancer in the absence of CTNNB1 mutations." (PMID 36292090, 2022). "We also cultured primary endometrial cells and endometrial cancer cell lines (Ishikawa and RL95–2), and observed the expression of S100P in these cells." (PMID 32883230, 2020). "Our laser confocal microscopy results showed the co-localized expression of S100P and EZRIN in endometrial cancer cells, which indicated that S100P might interact with Ezrin during the occurrence and progress of endometrial cancer." (PMID 32883230, 2020). "There was a gradual increase in the S100P signal as the disease progressed from normal endometrium and simple non-atypical hyperplasia, to complex non-atypical hyperplasia, atypical hyperplasia, and then to endometrial cancer." (PMID 32883230, 2020).
urothelial carcinoma (6 papers, 2014 to 2024). A malignant neoplasm derived from the transitional epithelium of the urinary tract (urinary bladder, ureter, urethra, or renal pelvis). "Immunohistochemical staining showed a similar profile of urothelial lineage with frequent positive expression of uroplakin II, GATA3, CK20, CK7, and S100P in both giant cell and conventional urothelial carcinomas." (PMID 39023556, 2024). "Nucleocytoplasmic immunoreactivity of S100P was detected in normal human urothelium and in urothelial carcinoma cells." (PMID 35648290, 2022). "Later work confirmed the high prevalence of S100P positivity in high-grade urothelial carcinomas (reviewed in." (PMID 35648290, 2022). "Additionally, they consider that high–molecular weight cytokeratin and P63 are more sensitive for the diagnosis of urothelial carcinoma compared with thrombomodulin and S100P." (PMID 27256178, 2016). "Standard discriminant analysis of this study demonstrated that, in descending order of importance for the urothelial lineage markers, UKP2, S100P, GATA3 and THBD were the most important predictors for urothelial carcinoma by gene expression." (PMID 33762601, 2021). "Furthermore, GATA3, p63, S100P, CK20, and uroplakin II are markers of urothelial carcinoma." (PMID 39310501, 2024).
cervical carcinoma (5 papers, 2014 to 2023). A carcinoma arising from either the exocervical squamous epithelium or the endocervical glandular epithelium. "S100P was found to be up-regulated in cervical cancer tissue from early and late stage patients as well as in HeLa cells." (PMID 29719595, 2018). "S100P was first isolated from human placenta and has a crucial role in several biological functions; however, its exact function in cervical cancer remains unclear." (PMID 29719595, 2018). "Furthermore, the expressions of S100P, S100A4, KRT7 and TGM2 were also induced by silencing of ACTL6A in cervical cancer cells." (PMID 34395295, 2021).
intrahepatic cholangiocarcinoma (5 papers, 2022 to 2025). A carcinoma that arises from the intrahepatic bile duct epithelium in any site of the intrahepatic biliary tree. "Through scRNA-seq analysis of intrahepatic cholangiocarcinoma, S100P and SPP1 are regarded as two biomarkers for two intrahepatic cholangiocarcinoma molecular subtypes." (PMID 36171879, 2022). "Indeed, a study on intrahepatic cholangiocarcinoma (ICC) revealed S100P and SPP1 as two potential biomarkers to study this tumour heterogeneity, with SPP1+ TAMs numerosity being particularly high in ICC peripheral small duct type compared to ICC perihilar large duct type." (PMID 40395129, 2025). "In our data, SPP1 was strongly expressed in intrahepatic cholangiocarcinoma and S100P had predominant expression in distal bile duct and gallbladder adenocarcinoma, but there were also many cells without either SPP1 and S100P expression." (PMID 39417106, 2024).
adenoma (4 papers, 2015 to 2025). A neoplasm arising from the epithelium. "We then analyzed S100P protein expression in adenomas and paired samples of normal mucosa and adenocarcinomas using a rabbit monoclonal antibody." (PMID 25585623, 2015). "A higher nuclear and cytoplasmic S100P expression in high-grade adenoma is compatible with its putative role in promoting cell proliferation and tumor progression." (PMID 25585623, 2015). "S100P overexpression was observed early in the adenoma stage, and its immunoreactivity was predominantly localized in the nucleus and to a lesser extent in the cytoplasm." (PMID 25585623, 2015). "All 35 adenomas showed a moderate to strong S100P overexpression compared to the surrounding glands." (PMID 25585623, 2015). "The early expression of S100P in adenoma indicates its important role in tumor initiation." (PMID 25585623, 2015). "It has been demonstrated that S100P is overexpressed early in the preneoplastic adenoma stage." (PMID 25585623, 2015). "Seventeen DEGs were observed during the transition from non-advanced adenoma to advanced adenoma, with genes such as FCGR1A and S100P showing reduced expression." (PMID 40003985, 2025).
bladder cancer (4 papers, 2019 to 2021). "Leupaxin (LPXN) is vital in tumourigenesis and the progression of bladder cancer by upregulating the expression of S100P via the PI3K/AKT pathway." (PMID 34439758, 2021). "Investigating S100 proteins in bladder cancer also revealed a correlation between S100P and drug resistance, as decreased S100P levels were found in cisplatin-resistant bladder cancer cells, whereas overexpression of S100P increased sensitivity to cisplatin." (PMID 32722137, 2020). "The S100 Calcium Binding Protein P was reported as a useful biomarker for PDAC based on IHC with expression already reported in gastric and bladder cancer." (PMID 32005189, 2020).